CXCL1 (C-X-C motif chemokine ligand 1)
Diseases named in the same sentence as CXCL1 in open-access papers (continued):
Sharing a sentence is not in itself a finding about the gene and the disease.
infection (continued). "Cytokine levels decreased for 6 of 9 assayed cytokines or the chemokine in the Chr7x3 AAB variant (IL-17a, IL-22, IL-5, IFN-γ, TNF-α, and IL-1β) and further decreased for all cytokines and the CXCL1 chemokine in the Chr7x3 ABB variant when compared to infection with Chr7x2 SC5314." (PMID 40577316, 2025). "Cytokine levels decreased for 6 of 9 assayed cytokines or the chemokine in the Chr7×3 AAB variant (IL-17a, IL-22, IL-5, IFN-γ, TNF-α, and IL-1β) and further decreased for all cytokines and the CXCL1 chemokine in the Chr7×3 ABB variant when compared to infection with Chr7×2 SC5314." (PMID 39896449, 2025). "Of note, the infection caused significant upregulation in mRNA expression level of interferon-stimulated genes (Isg15, Mx1, Mx2, Irf3, and Irf7) and pro-inflammatory cytokines (Tnf-α, Cxcl-1, and Il-6 genes)." (PMID 37929187, 2023). "Guided by our transcriptomic results indicating that a critical subset of inflammatory mediators are controlled by CASP11, we measured levels of CXCL1, IL-1β, and IL-6 by enzyme-linked immunosorbent assay (ELISA) in lung homogenates from infected animals at 2 and 4 d after infection." (PMID 35588457, 2022). "In addition, CCR5-deficiency during infection affected the upregulation of cytokine genes such as Csf2, Csf3, Cxcl1, Edn1, and Il6 and other genes associated with immune response (i.e., Gimap6, Mcoln2) and migration (i.e., Cyfip2)." (PMID 31506064, 2019). "Indeed, genes within the IL-17 pathway including Cebpb, Tnf, IL-6, Cxcl1, Cxcl2, Cxcl3, Cxcl5, Cxcl10, and Ccl7 were shown to be up-regulated in both susceptible and resistant mice during infection." (PMID 29339782, 2018). "It is true that CXCL1 causes infiltration by neutrophils, which do cause tissue destruction, and a reduction in neutrophil infiltration can contribute to uncontrollable pathogen infection, which may worsen the patient’s condition." (PMID 35806156, 2022). "Among them, the main role of Fprs in pathogenic infection is Fpr1/Fpr2 mediated neutrophil recruitment in bacterial infection, that is, in L. monocytogenes infection, Fpr1/2 directly chemoattract neutrophils through the receptor itself before CXCL1/2 is produced." (PMID 34899755, 2021). "Infection with WT + I trophozoites induced higher CXCL1 and lipocalin expression than ADI trophozoites, indicating a stronger host inflammatory response to acutely indole-exposed parasites." (PMID 41973754, 2026). "Surprisingly, some antiviral cytokines are elevated between week 5 and 12 post-infection including CXCL-1 and CXCL-10." (PMID 41516418, 2026). "Analysis of macrophage‐related cytokines and chemokines found that Tnf, Il1b, Il1a, Ilrn, Il17ra, Cxcl1, Cxcl2, Ccrl2, Ccl3, Ccl4, and Ccl9 expression significantly increased over the course of infection." (PMID 41117166, 2025). "The dissemination of CXCR2 and CXCL1 in murine pulmonary endothelial and epithelial cells following infection with K. pneumoniae was analyzed by transmission electron microscopy." (PMID 40413164, 2025). "We found that plasma CXCL1 levels were significantly elevated in patients with severe EV-A71 infection on the third day after infection onset." (PMID 39679722, 2025). "Bov342 infection resulted in upregulation of CXCL1, whereas VN1203 resulted in IFN-γ, IL-2, IL-5, and IL-10." (PMID 40410375, 2025). "They contribute to early host defense by producing cytokines and chemokines such as CXCL1 and GM-CSF, which facilitate the recruitment of additional neutrophils and macrophages to sites of infection." (PMID 40489568, 2025). "The expression of chemokines and cytokines, especially CXCL1 in astrocytes, was markedly induced after EV-A71 infection." (PMID 39679722, 2025). "This revealed increased CXCL1 release at 6 hours post-infection in CFTR-/- mice compared to controls." (PMID 39903773, 2025).
infection (continued). "Expression of genes such as Il17 and Cxcl1 was 5–10-fold lower after infection with Salmonella and C. albicans than infection with Salmonella alone, with an increase in arginase II (Arg2) expression." (PMID 40903573, 2025). "Although brain inflammation was limited in our model, cytokines, including G-CSF, CXCL10, CXCL1, IL-6, and IL-1β, were already increased in the periphery by day 3 post-infection, despite a low to undetectable viral load." (PMID 41472308, 2025). "The levels of CXCL10/IP-10 and IL-15 in BAL fluid peaked in both the lean and obese groups during the acute phase of infection, with CXCL1-/IP-10 levels exhibiting the most dramatic increase." (PMID 40027795, 2025). "In the context of infection, CXCL1 acts as a chemotactic signal, attracting neutrophils to the area where parasites are present." (PMID 40943268, 2025). "Early in infection, days 3 and 5, levels of the chemokines CXCL1 and CCL2 were also lower in the brains of co-infected mice." (PMID 39817772, 2025). "In mice infected with Δplp1 parasites, the CXCL1 levels plateaued and returned to pre-infection levels by 8 dpi, correlating well with total neutrophil numbers in the PECs." (PMID 40166190, 2025). "With l-arginine supplementation, induction of Il17 and Cxcl1 was significantly lower 24 h post-infection with Salmonella and mice lost more weight." (PMID 40903573, 2025). "From lung homogenate, we found elevated levels of CXCL1 in Ctsz−/− compared to B6 (p = 0.007), suggesting that the connection between Ctsz and CXCL1 extends beyond the context of infection." (PMID 40924769, 2025). "Analysis of inflammatory mediators in NHBE culture supernatants (Luminex multiplex assay) revealed that IL1β, IL1α, and CXCL1 were significantly elevated in NHBEA/A cultures compared to NHBEG/G cultures following infection with Cal/09 and HK/68." (PMID 40627391, 2025). "Conversely, Pad2−/− mice showed a downregulation of M1‐related genes (Il1a, Il1b, Tnf, Cxcl2, Ccl4, Il12a, Cxcl1, Il6) compared to WT mice after PA infection." (PMID 40087815, 2025). "Here, we show that lung CXCL1 levels are consistently elevated in Ctsz−/− mice prior to and throughout infection." (PMID 40924769, 2025). "CXCL1 attracts several immune cells, especially neutrophils, to the site of infection and thus regulates the immune responses." (PMID 40813994, 2025). "In dogs, KC-like is a chemokine similar to human and murine CXC motif ligand 1 (CXCL1) and attracts primarily neutrophils to sites of injury or infection." (PMID 40241810, 2025). "CXCL1 was elevated in the BALF at all post-infection timepoints in A/J mice and reached a peak average of 1385pg/mL at day 5 PI, nearly 11-fold greater than the levels of their B6 counterparts at that time point." (PMID 39823516, 2025). "ELISA of the supernatant after infection or combined treatment showed that Pg infection promoted the secretion of CXCL1 and CXCL8 proteins by HOKs, and acetylcholine exacerbated this process, further enhancing CXCL1 and CXCL8 secretions." (PMID 41358003, 2025). "One day after infection, the expression of Cxcl1, Cxcl2, Cxcl5, TNF-α, and IL-1β were 15 – 50-fold higher in lungs of Mki67WT mice exposed to hyperoxia when compared to Mki67WT mice exposed to room air." (PMID 40494897, 2025). "Subsequent production of IL-6, IL-12, and CXCL1 by neutrophils recruit additional adaptive cells to the site of infection." (PMID 39966757, 2025). "In the lungs, CXCL1 was significantly higher in the SFV-only infection at day 3, while CXCL10 was higher at 5 dpi." (PMID 39817772, 2025). "To test if macrophages contribute to the increased production of CXCL1 during infection in Ctsz−/− mice, we generated BMDMs from Ctsz+/+ and Ctsz−/− sibling pairs." (PMID 40924769, 2025). "CXCL1 is known for its role in recruiting neutrophils to the wound site, where they combat infection and initiate the inflammatory response." (PMID 40725137, 2025).
infection (continued). "Beta P20 infection was associated with greater inflammatory cytokine production (CCL2, CXCL1, IL-6) than P0 (p < 0.005, p = 0.051, p < 0.05, respectively)." (PMID 38365933, 2024). "The chemokine Cxcl1 recruits and activates neutrophils to combat infections and kills microorganisms in tissues." (PMID 39728387, 2024). "Cxcl1 lung mRNA increased 13.6-fold in the lungs of both wild-type and K-RasLA1 mice after infection with MHV68." (PMID 39338937, 2024). "The levels of MIP-1α, MIP-1β, IL-6, RANTES, MCP-1, and CXCL1 were significantly reduced in Adam9 KO compared to WT mice after infection." (PMID 38755212, 2024). "On the other hand, the increased levels of C3, IL-6, IL-12, TNFα and CXCL1 as a means of activation of innate-mediated response in early infection phases have been found in SARS-CoV-2-infected Caco-2 cells." (PMID 38886736, 2024). "In accordance with our findings, infection of OLMECs with BTV resulted in the upregulation of ENSOART00020004532 (CXCL1) expression, whereas the expression of TGFB1 was significantly downregulated." (PMID 39334220, 2024). "On the contrary, we found that the ECRG4 KO mouse infection had increased expression of IL1β (P = 0.0053), IL-6 (P = 0.047) and TNFα (P = 0.024), with a trend towards increased CXCL1." (PMID 39509414, 2024). "At 4 days post-infection, both the transcriptional level of CXCL1 in the kidney and the secretion of CXCL1 in the serum were higher in Trim26–/–mice." (PMID 38166150, 2024). "The chemokine CXCL1 is capable of attracting neutrophils and other immune cells to the infection site, thereby promoting immune regulation." (PMID 39409019, 2024). "For CXCL1, the increase was more pronounced with the ΔltaS mutant inducing a higher CXCL1 levels from 4 to 12 h of infection." (PMID 38504299, 2024). "Compared to the H99 strain infection, Cxcl1, which can recruit and activate neutrophils, and Ccl17, secreted by M2 macrophages to act on Th2 cells, showed a gradually increasing expression level in the lungs of mice infected with the cdh1Δ mutant strain." (PMID 39728387, 2024). "Similar to the findings in our transcriptional analysis, we found increased TNFα (P = 0.028) and CXCL1 (P = 0.0056) in the ECRG4 KO mouse infection, as well as a trend towards increased CXCL2, IL1β, and IL6." (PMID 39509414, 2024). "Using qPCR, we evaluated the expression of cytokines that are important for neutrophil recruitment to sites of infection, including IL1β, IL-6 and TNFα, as well as the neutrophil chemokines CXCL1 and CXCL2." (PMID 39509414, 2024). "K-RasLA1 and wild-type mice were infected with 40,000 pfu of MHV68 or mock-infected and harvested 7 days post-infection, a time of peak expression of Il-6, Csf3, and Cxcl1 mRNAs." (PMID 39338937, 2024). "Normalized to cell counts, Fnn infection of hypoxia conditioned cells showed a ~two-fold increase in IL-8 and CXCL1 secretion when compared to normoxia conditioned cells." (PMID 38720110, 2024). "Upon infection, macrophages produce mediators (CXCL1 and CXCL2) to recruit neutrophils to the site of infection and crosstalk between these two cell populations is key for the clearance of M.tb." (PMID 39649174, 2024). "Assessment of cytokines in the lung revealed that expression of Type 17 cytokines (Il-6, Cxcl1, Csf3) peaked at day 7 post-infection." (PMID 39338937, 2024). "Many of these factors, such as CXCL-1, play an important role in inflammation serving as chemoattractant for immune cells to fight infection." (PMID 38696307, 2024). "Infection with Spn significantly increased expression of Cxcl1, Cxcl2 and lipocalin-2 (Lcn2), a marker of inflammation, in infant mice compared to adults." (PMID 38718049, 2024). "We used acute infection with M. pneumoniae, and this modality results in a Th1-type immune response, so we screened for the presence of the Th1 cytokines IFN-γ, TNFα, functional IL-8 (CXCL1) in BALF following infection." (PMID 39759447, 2024).
infection (continued). "qPCR and Multiplex immunoassay performed in lung homogenates confirmed that, in line with cytospin analysis, infection at ZT12 was associated with lower levels of expression of pro-inflammatory cytokines TNFα, IL-6, and IL-1β and the chemokine CXCL1." (PMID 36896128, 2023). "Analysing all timepoints together in an unpaired analysis, there was a marked trend towards higher CXCL1, IL-8, IP-10 and lactoferrin during infection." (PMID 37862368, 2023). "Epithelial cells are known to produce various proinflammatory cytokines and chemokines that include CXCL1, IL-6, IL-8, as well as GM-CSF following infection with C. trachomatis." (PMID 36870960, 2023). "Several DEGs specific to cytokines Cxcl1, Cxcl2, Ccl3, and Il1b were upregulated in bone-marrow-derived macrophages at both 1 and 24 h post-infection with Bb validating the mRNA abundance observed in scRNA-Seq analysis of infected splenocytes." (PMID 38149246, 2023). "It has even been shown that n-3 PUFAs are able to modulate the production of CXCL1 and influence infection outcomes during the early stages of lung infection." (PMID 37686333, 2023). "These two cell types, typically defined by expression of Ly6g (neutrophils) and Adgre1 (F4/80, macrophages), expressed a similar transcriptional program following infection, including S100a8/9, Lcn2, Cxcl1, and Il1b." (PMID 38096412, 2023). "Twenty-four hours after infection, alcohol-fed mice produced significantly higher amounts of CXCL1 in BALF compared to infected untreated mice." (PMID 37275853, 2023). "Similar to 12 h, genes significantly upregulated in the later stages of infection were cytokines or chemokines, such as CXCL1, CXCL2, CXCL3, CXCL8, CXCL10, and CCL20." (PMID 37211158, 2023). "Here we demonstrated that increased bacterial load in alcohol-fed mice is associated with decreased leukocyte migration into the alveoli, reduced frequency of severe lung inflammation and systemic and local CXCL1 release during infection." (PMID 37275853, 2023). "Infection of BMDCs with EBs opsonized with male IgG enhanced expression of chemokines CXCL1, CXCL2, CXCL5 and pro‐inflammatory cytokines TNF, IL1β and IFNγ compared to uninfected or non‐opsonized controls." (PMID 38441219, 2023). "For molecular detection, CircZSWIM6 infection enhanced the expression of senescence markers p16 and p21, SASPs such as CXCL1 and IL‐6, decreasing aggrecan‐positive ECM components." (PMID 36604982, 2023). "Prior studies demonstrated that the activation of Cxcl1/Cxcl2 in murine macrophages is a key event during Bb infection." (PMID 38149246, 2023). "Upregulation of IL-17 in parenchymal cells induces recruitment of polymorphonuclear cells to the site of infection through CXCL1-mediated pathways." (PMID 37495756, 2023). "Infection of APCs with opsonized EBs enhanced expression of chemokines CXCL1, 2, 5 and pro‐inflammatory cytokines IL1β and IFNγ and TNF mRNA." (PMID 38441219, 2023). "After infection or injury, mast cells and macrophages synthesize and release the neutrophil chemokine CXCL1/CXCL2 (CXC chemokine ligand 1/2) to trigger the early stage of neutrophil recruitment in response to inflammation." (PMID 37266443, 2023). "CXCL1, IL-8 and IP-10 were higher in the second infection episode relative to the first (p = 0.0012, 0.044, and 0.04)." (PMID 37862368, 2023). "For example, following C. albicans fungal brain infection, microglia produced IL-1β and CXCL1 within 24 hours of infection, which elicited a significant influx of neutrophils to the brain to enable clearance of the infection." (PMID 37938547, 2023). "We found that CXC cytokines IL-8, IP-10 and CXCL1, and antimicrobial protein lactoferrin, were raised either during or following clinically inapparent infection." (PMID 37862368, 2023). "CXCL1, IL-8 and IP-10 were raised in the second infection episode relative to the first (p = 0.0012, 0.044, and 0.04, paired Wilcoxon signed-rank test, n = 20)." (PMID 37862368, 2023).
infection (continued). "CXCL-1 acts as a chemoattractant for immune cells, especially neutrophils to the site of injury or infection." (PMID 37946314, 2023). "EV chemokine CXCL1, which attracts neutrophils to regions of infection or injury, decreases with age in the total cohort." (PMID 37179299, 2023). "To understand the significantly increased bacterial load into alcohol-fed mice even in the presence of higher levels of NO and CXCL1, we decided to investigate inflammatory cell influx into the infection site." (PMID 37275853, 2023). "ELR-type chemokines activated by cp strain infection included CXCL1, CXCL3, CXCL5, CXCL8, and CXCL15." (PMID 35746747, 2022). "Conversely, CXCL1 levels were significantly increased in L3881-infected cells at 4 h post-infection (h.p.i)." (PMID 35898912, 2022). "CXCL1 is known to attract neutrophils to the site of infection, and the abundance of CXCL1 in diabetic wounds is high in diabetic patients in comparison to healthy controls." (PMID 36367946, 2022). "The present study systemically observed an increase in the expression of neutrophil chemoattractant CXCL1/Gro- upon single species implant infections, which was observed to increase in clinical studies and animal models during active bacterial infections." (PMID 35203495, 2022). "Neutrophils accumulated in the lungs of aged mice as early as day 1 post-infection, and this increase was maintained throughout the course of infection as compared with young mice and correlated with higher pulmonary CXCL1 and CXCL2 levels." (PMID 36233146, 2022). "Many chemokines are produced during the infection process, and specific cell types are recruited through several unique chemokine receptors, such as CXCL1, CXCL2, and CXCL8, which can recruit neutrophils." (PMID 35493728, 2022). "Infection led to robust induction of chemokine and interleukin genes, including Il1b, Il6, Ccl2, Ccl3, Ccl4, Ccl7, Cxcl1, Cxcl2, Cxcl5, Cxcl9, and Cxcl10, and related receptor genes, including Ccr1, Ccr4, Ccr5, Ccr5, Ccr7, Cxcr2, Cxcr5, Il1r2, and Il1rn." (PMID 35487885, 2022). "Collectively, these findings demonstrated that enhanced inflammation activation via the CXCL1/2–CXCR2–NLRP3–IL-1β axis and neutrophil recruitment occur in the lungs of beta variant-infected mice in the later stages of infection." (PMID 36005818, 2022). "IAV, or more precisely the NS1 of IAV, decreases the immune response in the lung to infection with this virus and thus decreases the expression of CXCL1/KC and CXCL2/MIP-2 there." (PMID 36613652, 2022). "Specifically, a reduction in virus-induced neutrophilic inflammation is likely explained by a reduction in the expression of CXCL1 (KC), a chemoattractant that mediates the recruitment and trafficking of neutrophils to the site of infection." (PMID 35601109, 2022). "While CXCL-1 expression was similar between the two infection routes of CDC1551-infected mice, CDC1551 i.c.vent." (PMID 35073927, 2022). "Syk-inhibited MΦ had diminished expression of type 1 cytokines/chemokines (Il12p40, Tnf, Il27p28, Cxcl1) during infection." (PMID 36678402, 2022). "We also demonstrated that enhanced inflammation activation via the CXCL1/2–CXCR2–NLRP3–IL-1β axis and neutrophil recruitment occurs in the lungs of beta variant-infected mice in the later stages of infection." (PMID 36005818, 2022). "Compared to RV-A1B, RV-C15 infection induced significantly higher mRNA expression of CXCL1, CXCL2, IL-5 and IL-13." (PMID 33968043, 2021). "Because intestinal epithelial cells secrete CXCL1 upon pathogen infection, we measured CXCL1 as a metric for assessing bacterial pathogenicity of bacteria within the lumen of the engineered intestinal epithelium." (PMID 33777849, 2021). "It is worth noting that a very early (i.e. 24-48 h p.i.)but transient expression of CCL2 and CXCL1 has also been reported upon infection by RSV, CMV and influenza virus." (PMID 33858301, 2021).